INS (insulin)
Diseases named in the same sentence as INS in open-access papers (continued):
Sharing a sentence is not in itself a finding about the gene and the disease.
Insulin resistance (continued). "Male HFD PN offspring had similar fasting blood glucose levels compared to control males (p = 0.6) but had a 16% greater area under the curve after insulin administration, suggesting some level of insulin resistance in this group (p = 0.003)." (PMID 34977118, 2021). "Previous studies on experimental models of insulin resistance revealed impaired insulin-mediated PI3K/Akt-dependent signaling in the vasculature." (PMID 34366875, 2021). "Insulin resistance has been shown to positively correlate with the neutrophil-lymphocyte ratio and plasma insulin concentration to positively correlate with the numbers of lymphocytes and monocytes." (PMID 34886800, 2021). "GP has great potential for treating T2DM by inhibiting insulin resistance, promoting insulin production, protecting islet B cells, and improving inflammation." (PMID 34122100, 2021). "Hepatic vagotomy diminishes insulin sensitivity (assessed as insulin-stimulated glucose uptake) in the insulin-sensitive state, while improving insulin sensitivity and glucose tolerance in a mouse model of insulin resistance." (PMID 34192533, 2021). "Overexpression of SIRT1 is able to rescue obesity-induced insulin resistance in POMC neurons of mice where insulin-resistant nuclear FOXO1 has become constitutive." (PMID 33806509, 2021). "When insulin resistance is elevated, pancreatic insulin secretion increases to normalize serum glucose levels, and if insulin secretion is insufficient, serum glucose concentrations increase and induce type 2 diabetes." (PMID 34359426, 2021). "Increased oxidative stress and inflammation will contribute to the development of insulin resistance and impaired insulin secretion." (PMID 33672171, 2021). "Along with the well-defined patterns of fasting [18F]-FDG-PET changes that occur in AD, recent evidence has shown alterations in fasting and insulin-stimulated brain glucose metabolism also in obesity and systemic insulin resistance." (PMID 33917464, 2021). "The effects of EC specific insulin resistance have been assessed using a transgenic mouse with endothelial overexpression of an insulin resistant mutant IR (ESMIRO)." (PMID 34571964, 2021). "This review combines and interlinks the defects in the insulin signal transduction pathway of the insulin resistance state with special emphasis on the AGE-RAGE-NF-κB axis." (PMID 34445300, 2021). "At the same time, the medians of insulin levels and the calculated indices of insulin resistance (Disse, QUICKI, and Revised-QUICKI) were comparable." (PMID 34442446, 2021). "T2DM is a metabolic disease characterized by chronic insulin resistance and pancreatic β-cell dysfunction, leading to impaired insulin release and hyperglycemia." (PMID 33832546, 2021). "In this study, we developed an insulin-resistant zebrafish model by excess insulin-induced insulin resistance." (PMID 34358068, 2021). "Insulin resistance was significantly relieved by CQEt supplementation as indicated by a decrease in plasma insulin and glucose and insulin resistance indices (HOMA-IR, QUICKI, FIRI)." (PMID 34441028, 2021). "The publicly available cohort database lacks insulin level measurements and cannot be analyzed for insulin resistance." (PMID 34993251, 2021). "Dpp4 inhibitors increase the biological activity of incretin hormones, thereby increasing the half-life of insulin and improving insulin resistance." (PMID 34094026, 2021). "Regarding the subgroup analysis of different pregnant women, the effects of probiotics on FPG, insulin, and insulin resistance were more obvious among GDM and healthy women than among overweight/obese women." (PMID 34603479, 2021). "It was formerly demonstrated that NFkB-dependent inflammation is an important trigger of endothelial insulin resistance and inhibition of this protein ameliorates transductional cascade of insulin and extends lifetime in mice." (PMID 33935754, 2021).
Insulin resistance (continued). "Insulin signaling pathway, especially insulin resistance, is positively correlated with the aggressiveness of EC and local tumor dissemination." (PMID 33763366, 2021). "The pathway analysis also revealed that there was a correlation with several insulin-related enrichment pathways, including type II diabetes mellitus, insulin secretion and insulin resistance." (PMID 34905699, 2021). "Findings revealed significant reductions in fasting insulin (p = 0.0002) and homeostatic model of assessment of insulin resistance (p = 0.0003) following the high dose strawberry phase when compared to the low dose strawberry and control phases." (PMID 33922576, 2021). "Insulin resistance is induced by decreased responsiveness of individual peripheral tissues, such as skeletal muscle, fat, and liver tissues, to the action of insulin." (PMID 34641407, 2021). "Chronic hyperinsulinemia alters the insulin signaling pathway and increases insulin resistance in the brain with reduced uptake of insulin transport across the blood-brain barrier (BBB) induces cognitive dysfunction with dementia." (PMID 34183987, 2021). "Studies show that glucocorticoids can induce insulin resistance by directly interfering with insulin signaling in skeletal muscle." (PMID 32647998, 2020). "Most obese subjects who have insulin resistance are able to compensate for it by increasing insulin released by ß-cells of the pancreas." (PMID 32183037, 2020). "Early insulin treatment has been recommended for older persons with T2D; however, older adults with T2D who refuse insulin therapy tend to have higher psychological insulin resistance than do those who have already received insulin." (PMID 32257276, 2020). "Omega-PUFA prevent and reverse high-fat diet-induced inflammation and insulin resistance in adipose tissue, increase glucose-stimulated insulin secretion, and decrease prostaglandin production, which in turn enhances the secretion of insulin." (PMID 33322303, 2020). "Previous study has indicated that the deficiency of ERK displays protective effect on insulin resistance and obesity, and the JNK signaling is also involved in the secretion of insulin." (PMID 32928312, 2020). "The serum concentration of asprosin was positively correlated with FBG, HbA1c, TAG, insulin resistance indices (HOMA-IR) and CVDs risk factor (TC/HDL-C) and was negatively correlated with insulin sensitivity indices (HOMA-S, and QUICKI) in T2DM patients." (PMID 32714446, 2020). "Insulin resistance is defined as the perturbation of insulin-mediated signaling pathways, leading to systemic hyperglycemia." (PMID 32842547, 2020). "Overall, the subjects with insulin resistance presented greater values of chemerin—9.05 ± 5.1 pg/mL (median value 8.2 pg/mL) vs. 8.6 ± 7.54 pg/mL (median value 5.6 pg/mL) in insulin-sensitive subjects." (PMID 32858998, 2020). "One method involves suppressing the occurrence and development of DCM by lowering the blood glucose concentration and insulin resistance, using hypoglycemic drugs such as sulfonylurea, α-carbosidase inhibitors, biguanides, and insulin." (PMID 33597877, 2020). "Insulin resistance is characterized by a restriction in the ability of insulin to exert its physiological functions in tissues, leading to insulin hypersecretion by the pancreas as a compensatory mechanism to maintain glucose homeostasis." (PMID 32230887, 2020). "Hepatic insulin resistance has been characterized by a reduction of insulin-stimulated signal transduction pathways for hepatic glucose production, including insulin receptors and downstream mediators." (PMID 32591906, 2020). "Accumulation of intramyocellular lipid (IMCL) is observed in individuals with insulin resistance as well as insulin-sensitive endurance athletes with high peak oxygen consumption (VO2peak), which is called the athlete’s paradox." (PMID 32139784, 2020).
Insulin resistance (continued). "T2DM factors such as a longer disease duration, diabetic complications, poor glycemic control, insulin resistance (IR), and the use of insulin or oral antidiabetic medication have a complex pathophysiological interaction with fractures." (PMID 32083133, 2020). "Among the currently available synthetic drugs that target the dual metabolic defects of type 2 DM that are impaired insulin secretion and insulin resistance, some of these drugs produce some serious side effects at high doses." (PMID 33335883, 2020). "Obesity is often characterized as low-grade chronic inflammation with irregular inflammatory response, weak antioxidant capability, and low insulin sensitivity, resulting in inflammation, oxidative stress, and insulin resistance." (PMID 33266002, 2020). "Insulin resistance is the inability of a cell to respond adequately to insulin signaling, resulting in decreased glucose uptake by the cell." (PMID 32170854, 2020). "The is consistent with previous studies reporting that dietary propolis can improve insulin sensitivity in the early stage of insulin resistance developed in different mice models, suggesting that the effect of propolis on glucose control is universal." (PMID 32235581, 2020). "In obese patients assessed for insulin resistance, the magnitude of lower insulin clearance coincided with a progressive increase in blood insulin levels." (PMID 32860984, 2020). "In comparison with casein, soy protein reduced fasting glucose and insulin levels in animals and prevented insulin resistance induced by a high-sucrose diet." (PMID 33042976, 2020). "Together with the GTT and ITT results, the results obtained suggest that the pathological effects of apoE4 are mediated by two complementary mechanisms: reduced ability to secrete insulin and increased insulin resistance." (PMID 32075060, 2020). "On the other hand, the GTT glucose and insulin values in the offspring of HFD mothers suggested a state of mild insulin resistance." (PMID 32407841, 2020). "All studies included in this meta-analysis were carried out among Caucasian diabetic patients (no East Asians included); however, the majority of East Asian diabetic patients showed insulin resistance with central obesity and defect in insulin secretion." (PMID 33257645, 2020). "Generally, the mechanism of insulin resistance results from defective insulin action at target cells." (PMID 32796572, 2020). "In the preclinical phase of T2DM, insulin resistance is initially compensated for by increased insulin secretion; however, this prolonged overstimulation of insulin secretion causes the gradual failure of β-cells over time." (PMID 32425738, 2020). "Over a median follow-up of 7.2 years, the association remained significant even after adjustment for the risk factors, including BMI, hypertension, glucose, and lipids, as well as adjustment for insulin level, another marker of insulin resistance." (PMID 32957570, 2020). "When insulin secretion is insufficient to compensate for the insulin resistance, type 2 diabetes emerges." (PMID 33067534, 2020). "Another study suggests that glutamine, leucine, and arginine activate mTORC1 and a high activation of mTORC1 in the muscle inhibits insulin signaling and contributes to systemic insulin resistance." (PMID 33322303, 2020). "Serum/plasma concentrations of glucose, insulin (with the calculation of homeostatic model assessment insulin resistance—HOMA-IR), estradiol, total testosterone, sex hormone-binding globulin (SHBG) and sclerostin were measured." (PMID 32592042, 2020). "Upregulation of miR29a and miR30 has been found in peripheral blood mononuclear cells from patients with gestational diabetes, and seems involved in insulin signaling, angiogenesis, insulin resistance and adipose tissue dysfunction." (PMID 32635492, 2020).
Insulin resistance (continued). "The manifestation of insulin resistance in skeletal muscle occurs due to reduced insulin-stimulated glucose uptake as well as impaired post-receptor and intracellular signalling pathways." (PMID 31968625, 2020). "For instance, it is known since long time that insulin clearance is inversely related to insulin resistance." (PMID 33324238, 2020). "The Sirt1 gene is known to serve as a key energy redox sensor involved in generating ATP that helps promote glucose-stimulated insulin secretion in pancreatic β-cells and potentially contribute to β-cell adaptation in response to insulin resistance." (PMID 32599958, 2020). "Podocytes are also insulin sensitive and can develop insulin resistance, as revealed by the inability of podocytes isolated from diabetic mice to respond to insulin stimulation by phosphorylating Akt." (PMID 33321755, 2020). "We observed lower serum levels of IL-6, suggesting moderate inflammation and immune response, and lower fasting insulin levels in serum, indicating the amelioration of insulin resistance, in the CR group compared with the ad libitum-fed (AL) group." (PMID 31927537, 2020). "Here, signatures of insulin resistance or fat body insulin sensitivity revealed only partial recovery, but the extent of growth restoration observed in these animals was comparable with wild types raised on a regular diet." (PMID 32849518, 2020). "Type 2 diabetes is characterized as insulin resistance, namely the body's sensitivity to reduced insulin levels, resulting in excessive accumulation of insulin in the plasma." (PMID 31993159, 2020). "In agreement with the previous study, our results showed upregulated NNMT, which correlates positively with insulin resistance, and downregulated GNMT, deficiency of which is known to impair glucose tolerance and insulin sensitivity." (PMID 32518576, 2020). "Abnormal lipid metabolism contributes to insulin resistance by perturbing insulin signaling pathways." (PMID 32922365, 2020). "SPs dose-dependently improved glucose regulation by potentiating insulin secretion and reducing insulin resistance in our lean T2DM rat model." (PMID 31991596, 2020). "The brain, especially neurons, is one of the major targets of insulin and is particularly vulnerable to insulin resistance." (PMID 33344443, 2020). "Peripheral insulin resistance leads to decrease insulin signaling in CNS, followed by alteration in brain metabolism." (PMID 32365816, 2020). "In response to postweaning HF diet, serum insulin level and the homeostasis model assessment of insulin resistance (HOMA-IR) were increased in control offspring." (PMID 32316103, 2020). "Insulin resistance (IR) is an important defect associated with obesity and T2DM, which is defined as ‘a relative impairment in the ability of insulin to exert its effects on glucose and lipid metabolism in target tissues’." (PMID 32467715, 2020). "Although there is a growing understanding of the relationship between protein intake during pregnancy and maternal insulin resistance, very little is known about the relationship between protein intake during pregnancy and offspring insulin sensitivity." (PMID 32397092, 2020). "Insulin resistance in Type II diabetes has been characterized by several defects in the insulin signaling cascade." (PMID 32670384, 2020). "In the present study, adipocytes were treated with TNF-α for 24 h to induce insulin resistance, which exhibited impaired insulin-stimulated glucose uptake and insulin signaling." (PMID 33390968, 2020). "Original exploratory experiences demonstrate that 6 weeks-exposure of lean mice to CIH is characterized by systemic insulin resistance and translates into adipocyte insulin signaling alterations." (PMID 33324235, 2020). "This study showed that TTK enhanced memory function with potentiated hippocampal insulin signaling, reduced insulin resistance, and improved gut microbiota in amyloid-β infused rats in an AD animal model." (PMID 32326255, 2020).
Insulin resistance (continued). "Insulin resistance is observed when higher than normal insulin concentrations are needed to achieve normal metabolic responses or when normal insulin concentrations fail to achieve a normal metabolic response." (PMID 33381523, 2020). "Pathological levels of ROS can activate NOX2 and the stress-sensitive serine/threonine kinase (JNK) in β cells and attenuate the insulin cascade, thus increasing insulin resistance." (PMID 32927712, 2020). "Plasma asprosin levels were increased in patients with glucose dysregulation and correlated with insulin resistance and first-phase insulin secretion." (PMID 32982804, 2020). "On the other hand, dysregulation in peripheral insulin signaling was previously reported, with high-5HT animals showing glucose intolerance and insulin resistance in comparison to low-5HT subline." (PMID 32269507, 2020). "Proinflammatory cytokines such as TNF-α and IL-1β exacerbate insulin resistance, while anti-inflammatory cytokines such as IL-4 and IL-10 promote insulin sensitivity." (PMID 32604889, 2020). "The insulin signaling pathway and insulin resistance were detected as affected in AMA and POR patients." (PMID 33511114, 2020). "These cytokines impair insulin signaling and peripheral glucose uptake and contribute to insulin resistance, lipolysis, and hepatic glucose production." (PMID 32660119, 2020). "Hepatic response to insulin and glucagon is dysregulated in subjects with insulin resistance and type 2 diabetes." (PMID 32466765, 2020). "Skeletal muscle is responsible for up to 80% of insulin-stimulated glucose uptake in healthy individuals, but glucose uptake in skeletal muscle of diabetic patients is severely impaired owing to insulin resistance." (PMID 32472192, 2020). "Further, these effectors should be considered in the context of insulin resistance since seminal research showed that variability in hepatic insulin clearance was a better predictor of insulin sensitivity than fasting insulin in dogs." (PMID 32860984, 2020). "Diacylglycerol (DAG) and ceramide have been suggested to be the two major lipids involved in hepatic insulin resistance via activation of protein kinase and downstream impairment of hepatic insulin signaling." (PMID 32728230, 2020). "In males, gonadectomy, on the contrary, increased the blood estradiol level, decreased blood insulin leveland insulin resistance." (PMID 33659826, 2020). "The relative insufficiency of insulin secretion and insulin resistance are also typical characteristics of T2DM." (PMID 32266256, 2020). "Plasma glucose and insulin concentrations decreased during deployment, resulting in reduced whole-body insulin resistance, assessed by HOMA-IR." (PMID 31952273, 2020). "For example, people with insulin resistance and glucose intolerance had a higher inflammatory tone and an altered response to respiratory viral infections compared to insulin sensitive individuals." (PMID 33178196, 2020). "Insulin resistance (Insulin Resistance, IR) refers to the decreased sensitivity of insulin target tissue (adipose tissue, skeletal muscle, liver) to insulin." (PMID 32964053, 2020). "In order to maintain glucose homeostasis despite insulin resistance, the maternal β-cells compensate by increasing total cell number, insulin synthesis, and insulin secretion." (PMID 32679915, 2020). "We also found that both nitric oxide and glutathione are fundamental for maintaining normal insulin action, as their levels are impaired in the early stages of insulin resistance." (PMID 32942712, 2020). "In this regard, a long-term treatment with RES was confirmed to improve insulin sensibility, reduce insulin resistance, and lower blood glucose levels." (PMID 33218062, 2020). "ER stress reportedly can inhibit the insulin signaling pathway, promote insulin resistance, and further accelerate T2DM progression." (PMID 33329383, 2020).